CD5 (CD5 molecule)
Diseases named in the same sentence as CD5 in open-access papers (continued):
Sharing a sentence is not in itself a finding about the gene and the disease.
lymphoma (continued). "The addition of metformin significantly decreased the M2 proportion and the CD36 expression level in the coculture systems, indicating that metformin could target altered lipid metabolism and decrease M2 macrophages in DLBCL, especially in CD5+ non-DE lymphoma." (PMID 36276140, 2022). "Lymphoma cells were small in size with mature chromatin, and positive for CD19, CD20, PAX5, and BCL-2, and negative for CD5, CD10, CD23, cyclin D1, and LEF1 (by IHC and/or flow)." (PMID 41357579, 2025). "In HSTCL, the lymphoma cells are typically double negative (CD4−CD8−) even if a subset of cases are CD8+, positive for CD3, CD2, CD7, and negative for CD1a and CD5." (PMID 38790955, 2024). "The following morning, CSF immunphenotyping revealed a clonal population of kappa light chains restricted B cells, which were CD5 and CD10 negative, consistent with CNS involvement by lymphoma, in keeping with a diagnosis of Bing–Neel syndrome (BNS)." (PMID 37151950, 2023). "Our results indicated that the expression pattern of CD22, CD23, FMC-7, and CD5 allowed us to accurately and differentially diagnose the B-CLL, MCL, and CD5-/CD10- lymphoma, while it was not capable of differentiating MCL from atypical CLL." (PMID 36624655, 2023). "With respect to immune cells, reports have demonstrated that in lymphoma, the absence of SPARC promotes aberrant interactions between NETs and CD5+ B cells." (PMID 37958984, 2023). "Immunohistochemistry stains of lymphoma cells were positive for CD20, CD79a, CD10, MUM1, BCL6, C-MYC, and negative for BCL2, cyclin D1, CD5, and CD3." (PMID 36120205, 2022). "The lymphoma cells were positive for CD79a, PAX5, CD10 (diffuse), BCL‐6, MUM1, MYC, BCL‐2, CD3 (subset) and CD5 (subset), and negative for TdT and CD61, with a proliferation index of 80%." (PMID 36467806, 2022). "Lymphoma cells in γδHSTCL showed blast-like morphology and were typically positive for moderate CD2, surface CD3, CD7, and TCRγδ, and weak-to-negative CD5." (PMID 35299754, 2022). "In dogs, immunocytochemistry and immunohistochemistry are commonly applied to discriminate between T-cell (CD3+ and/or CD5+) and B-cell (CD79a+ and/or CD20+) lymphoma, but are not suitable to detect phenotypic aberrancies." (PMID 35448684, 2022). "Flow cytometry classified the lymphoma as a double-negative phenotype of T-cell lymphoma (CD3+ and CD5+, but CD4- and CD8-) present in the duodenum and liver and suspected in the spleen which has previously not been reported in cats." (PMID 34925932, 2021). "The lymphoma cells express CD2 and CD3e, but usually not CD3s or other T-cell markers (CD4, CD5, and CD8)." (PMID 34702349, 2021). "Immunohistochemically, these lymphoma cells were positive for CD20, PAX-5, MUM-1, BCL-6 and CD5, but negative for CD3 and CD10." (PMID 32513269, 2020). "In two of the 3 CD4+ lymphomas (#9 and #10, 66.7%), an aberrant phenotype was found, with 60.8 and 87% of cells, respectively, staining positive for CD4, but mostly negative for CD5." (PMID 32903608, 2020). "An incisional biopsy from the left lacrimal gland revealed diffuse and intense CD20, CD5, and bcl-2 positivity with negative cyclin D1 and CD23 which supported lymphoma." (PMID 27738539, 2016). "None of these four CD5-positive cases showed presence of either C-MYC or BCL2 gene rearrangements; however, two patients fulfilled phenotypic criteria for double-hit lymphoma, expressing bcl2 or c-myc above the respective cutoff scores." (PMID 26071053, 2015).
lymphoma (continued). "The lymphoma cells of all eight MALT lymphoma cases were positive for Bcl2 and negative for CD5, CD23, CD10, Bcl6, MUM1, and CD25." (PMID 22395482, 2012). "We describe the case of a patient with discordant lymphoma characterized by the coexistence of splenic MCL and a CD5-negative non-Hodgkin lymphoma involving both the bone marrow and peripheral blood and compatible with a MZL." (PMID 21943040, 2011). "Consistently, lymphomas were Pax5+, B220+, CD43+, AA41+, CD69+ and negative for surface heavy or light chain immunoglobulins, CD5, CD4, CD8, CD23, CD21, BCL6." (PMID 16563162, 2006). "In cutaneous lymphoid infiltrates, the presence of a CD5- and CD23-positive B-cell population with a CLL/SLL phenotype supports secondary involvement by systemic leukemia/lymphoma rather than a PCMZL, which more typically shows a plasma cell-rich infiltrate with light-chain restriction." (PMID 41573437, 2025). "However, our patient showed some clinical and pathological features common to HSTCL diagnosis such as splenomegaly, lymphoma cells expression of TCR γδ, lack of CD5, and elevated alkaline phosphatase." (PMID 38790955, 2024). "Lymphoma cells are usually positive for: CD7, CD3, CD2, CD8, CD56 and negative for CD4, CD5, CD30." (PMID 39317016, 2024). "BM flow cytometry gating on the lymphoma cells confirmed the positive expression of CD2, CD3, CD7, CD8, CD56, T‐cell receptor (TCR) alpha‐beta chains, perforin, granzyme B, and negative for CD34, CD4, CD5, and TCR gamma‐delta chains, consistent with natural killer (NK)/T lymphoma involvement." (PMID 37206287, 2023). "They found that CD22, CD23, FMC-7, and CD5 expression could be used to diagnose CLL, MCL, and CD5−/CD10− lymphoma but could not differentiate MCL from atypical CLL." (PMID 37760396, 2023). "Immunohistochemistry of intrathoracic biopsy revealed that the tumor cells were positive for CD20, CD30, c-Myc, BCL-2, Mum-1, and PD-L1 but negative for CD3, CD5, CD10, BCL-6, PD-1, and cyclin D1, conforming to the pathological diagnosis of diffuse large B-cell lymphoma (DLBCL))." (PMID 33564306, 2021). "We found that, with one exception (mouse 353), all of the lymphoma cells stained positive for CD19, CD45R/B220 and high AA4.1 (CD93) expression and negative for CD5 and CD3, indicating that they are early stage B-cells, either surface IgM− or IgM+, in both Mtap+/+ and MtaplacZ/+ mice." (PMID 23840755, 2013). "In contrast, in T-lymphoblastic leukemia/lymphoma, the neoplastic cells may be negative for surface CD3 staining or positive, but variable CD3 is usually not observed, and the expression of pan T cell antigens, including CD2, CD5, and CD7, may be absent, but not variable." (PMID 40227608, 2025).
mantle cell lymphoma (91 papers, 2008 to 2026). Mantle cell lymphoma is a rare form of malignant non-Hodgkin lymphoma affecting B lymphocytes in the lymph nodes in a region called the ``mantle zone''. "Aberrant CD5 expression is a hallmark of several subtypes of non-Hodgkin’s lymphomas including mantle cell lymphoma." (PMID 39316441, 2024). "Studies of CD5 in some subsets of B-cell lymphomas, such as follicular lymphoma, diffuse large B-cell lymphoma, and mantle cell lymphoma, have demonstrated that the expression of CD5 is associated with a worse clinical outcome, whereas loss of CD5 expression is associated with better survival." (PMID 39410047, 2024). "Expression of CD5 in tumor cells is more frequent in LBCLs devoid of an intravascular component and does not portend an association with chronic lymphocytic leukemia or mantle cell lymphoma." (PMID 33499258, 2021). "Mantle cell lymphoma (MCL) is a mature B-cell lymphoma associated with cyclin D family rearrangements and typically expresses CD5 and cyclin D1." (PMID 38938449, 2024). "Mantle cell lymphoma (MCL) is derived from naïve CD5+ B-cells with the cytogenetic hallmark translocation 11;14." (PMID 33541390, 2021). "The expression of CD5 can also be observed in other lymphoid malignancies, such as mantle cell lymphoma." (PMID 39871707, 2025). "CD5 expression is possible but mantle cell lymphoma (including CCND1-negative MCL) should be excluded." (PMID 37530792, 2024). "It is distinguished from follicular lymphoma by negativity for CD10 and Bcl-6, from mantle cell lymphoma by negativity for CD5 and Cyclin D1, and from nodular sclerosing Hodgkin lymphoma by lack of CD30-positive lacunar cells (Reed–Sternberg cells)." (PMID 28353588, 2017). "In B-cell neoplasms, CD5 is usually expressed in chronic/small lymphocytic lymphomas (CLLs/SLLs) and mantle cell lymphomas (MCLs), for which the normal counterparts are considered to be CD5-positive B cells." (PMID 28380441, 2017). "Another subtype of NHL, mantle cell lymphoma (MCL) is an aggressive disease that is characterized by the abnormal accumulation of CD20+CD5+ B cells in the lymph nodes, spleen, bone marrow, and blood." (PMID 24955247, 2014). "Mantle cell lymphoma (MCL) is a malignant lymphoproliferative B-cell disorder derived from naïve pregerminal center CD5+ cells." (PMID 22592113, 2012). "For example, it has been reported that patients with CD5+ mantle cell lymphoma have poor prognosis." (PMID 40973845, 2025). "Mantle cell lymphoma (MCL) originates from naïve CD5+ B lymphocytes or, as is believed following more recent studies, from B lymphocytes that have indeed encountered the antigen but not in the context of the germinal center and have not then developed somatic hypermutations." (PMID 38534887, 2024). "Mantle cell lymphoma is an aggressive B cell neoplasm characterized primarily by a monotonous proliferation of small-to-medium-sized lymphocytes coexpressing CD5, CD20, and cyclin D1 epitopes and frequently presents chromosomal translocations, t(11 14) (q13; q32)." (PMID 38698463, 2024). "The other B-cell lymphoma type with frequent CD5 expression is mantle cell lymphoma (MCL)." (PMID 38535060, 2024). "Likewise, the use of anti-CD5 and anti-CD20 antibodies, coupled to NIR emitting NPs allowed the detection of CD5+ CD20+ mantle cell lymphoma." (PMID 34539653, 2021). "We report a case of mantle cell lymphoma with non-nodal clinical presentation, aberrant loss of CD5 expression, and concomitant cytogenetic deletion of 17p." (PMID 32257467, 2020). "Mantle cell lymphoma (MCL) is a CD5-positive, CD23-negative B cell malignancy accounting for 6% of all non-Hodgkin lymphomas (NHL) and carries a poor prognosis, with a median survival of only 4–5 years." (PMID 37373427, 2023). "CD5 is usually expressed in chronic lymphocytic leukemia,mantle cell lymphoma (MCL), and less frequently in DLBCL." (PMID 31814435, 2019).
mantle cell lymphoma (continued). "Mantle cell lymphoma (MCL) is a clinical entity characterized by the proliferation of CD5-positive antigen-naïve pregerminal centre B cells within the mantle zone that surrounds normal germinal centre follicles." (PMID 23762653, 2013). "Mantle-cell lymphoma (MCL), a CD5+ B-cell malignancy clinically more aggressive than CLL, is unlikely to develop BTK mutations during treatment with ibrutinib." (PMID 41213958, 2025). "Although the original diagnosis in this patient was CD5-positive DLBCL presumably transformed from the patient’s reported CLL/SLL, the presence of IGL::CCND2 raises the possibility of mantle cell lymphoma at initial diagnosis." (PMID 41374977, 2025). "In contrast to TCLs, the expression of CD5 in B-cell neoplasms is far less common and classically indicative of chronic lymphocytic leukemia (CLL) or mantle cell lymphoma (MCL)." (PMID 39410047, 2024). "Mantle cell lymphoma expresses B cell markers (CD20 and CD79a), T cell markers (CD5), and cyclin D1." (PMID 38698463, 2024). "Mantle cell lymphoma (MCL), which makes up approximately 5–10% of all lymphomas, is a subtype of B-cell lymphoma derived from CD5-positive, antigen-naïve, pre-germinal center B cells within the mantle zone that surrounds normal germinal center follicles." (PMID 37718438, 2023). "Biomarkers, including CD5, cyclin D1 and SOX-11, are useful for the differential diagnosis of mantle cell lymphoma from other B-cell NHLs." (PMID 34442137, 2021). "Mantle cell lymphoma (MCL) is an aggressive non-Hodgkin B-cell lymphoma typically expressing CD19, CD20, CD5, FMC-7, CyclinD1, and SOX-11 and harboring the IgH/CCND1 translocation." (PMID 30627460, 2018). "Mantle cell lymphoma, which is derived from B-cell lymphoma, is a subtype of non-Hodgkin's lymphoma, and the immune phenotype is a mature B-cell phenotype (CD20+, CD5+)." (PMID 29682183, 2018). "Atypical CLL is most frequently confused with mantle cell lymphoma (MCL), which co-expresses CD5 and CD19 similarly to CLL." (PMID 28713070, 2018). "Mantle cell lymphoma expresses B-lymphocyte markers (CD20 and CD79a), T-lymphocyte markers (CD5), and cyclin D1." (PMID 28705174, 2017). "Mantle cell lymphoma (MCL) is an aggressive and often-relapsing disease characterized by the clonal proliferation of CD5+ antigen-naive pre-germinal center B cells that form solid tumors and also enter the peripheral blood through a process called leukemization." (PMID 27662204, 2016). "The small lymphoid aggregates noted in his bone marrow were neoplastic in nature and represented bone marrow involvement by a CD5-negative mantle cell lymphoma (MCL) that presented without any associated lymphadenopathy." (PMID 22953080, 2012). "The differential diagnosis of CD5-positive MALT lymphoma and cyclin D1-negative mantle cell lymphoma is very difficult." (PMID 22333190, 2012). "They stressed the differential diagnosis between CD5-positive MALT lymphoma and mantle cell lymphoma." (PMID 22333190, 2012). "CD5 negativity helps distinguish SMZL from CLL and mantle cell lymphoma." (PMID 40777708, 2025). "The main differential diagnosis is mantle cell lymphoma (MCL): CD5+, but classically negative for CD23 and CD200 with strong expression of CD20 and immunoglobulins." (PMID 40347842, 2025). "Mantle cell lymphoma (MCL) is characterized by monomorphic small to medium-sized lymphoid cells with irregular nuclei and the CCND1 translocation, originating from peripheral B lymphocytes of the inner mantle zone, CD5+, and SOX11+ in the classical form." (PMID 36358737, 2022). "A diagnosis of small B cell lymphoma was rendered, with an offered differential diagnosis including CLL, marginal zone lymphoma, mantle cell lymphoma (CD5 negative), follicular lymphoma (CD10 negative), and lymphoplasmacytic lymphoma." (PMID 30755837, 2018).
mantle cell lymphoma (continued). "CD200 was uniformly expressed on CLL leukemic cells while, in mantle cell lymphoma (MCL) cases, CD200 was only expressed in a minority of CD5 positive cells in a small subset of patients and totally absent in most cases, suggesting its value in the differential diagnosis between CLL and MCL." (PMID 26910908, 2016). "Atypical MBL displays CD5 positivity along with higher expression of CD20 and other immunophenotypic features different from typical CLL-like MBL cells, resembling the immunophenotype of mantle-cell lymphoma." (PMID 25295254, 2014). "A diagnosis of secondary acute myeloid leukemia (AML) evolving from primary myelofibrosis (PMF) and concomitant CD5-negative mantle cell lymphoma (MCL) was rendered." (PMID 22953080, 2012). "Immunohistochemically, the low and intermediate grade B-cell lymphomas show the following immunophenotypes: follicular lymphoma, CD5-, CD10 +, CD23 -, CD43 -, cyclin D1 -; MALT lymphoma, CD5-, CD10-, CD23-, CD43+/-, cyclin D1 -; mantle cell lymphoma, CD5+, CD10-, CD23-, CD43 +/-, cyclin D1 +." (PMID 22333190, 2012). "Based on the results obtained, the differential diagnosis for this case included CD5-positive MALT lymphoma, cyclin D1-negative mantle cell lymphoma (MCL), or chronic lymphocytic leukemia (CLL)." (PMID 41262807, 2025). "By IHC, mantle cell lymphoma is positive for CD5 and cyclin D1 and is negative for CD10 and CD23." (PMID 37958219, 2023). "The neoplastic cells of mantle cell lymphoma (MCL) usually express CD5 and not CD10." (PMID 35186599, 2022). "To develop the use of nanomaterials as specific markers for the medical imaging of mantle cell lymphoma, we modified the surface of UCNPs by oxidation so that the CD20 or CD5 antibody could covalently attach to the upconversion nanoparticles to form antibody-UCNP conjugates." (PMID 29682183, 2018). "These included mantle cell lymphoma (MCL) cases (3/26, 11.5%), CD5-negative B-cell lymphoproliferative disorder cases (4/26, 15.4%), and cases with unusual immunophenotypic features (2/26, 7.7%)." (PMID 40427185, 2025). "Primary cutaneous mantle cell lymphoma (MCL) is a rare cutaneous proliferation of naive pregerminal CD-5 positive B cells in the skin with no extracutaneous involvement." (PMID 23762653, 2013). "Mantle cell lymphoma (MCL), an aggressive B cell malignancy, is characterized by the abnormal proliferation and accumulation of CD5/CD20/CD22 positive, CD23 negative B cells in various hematopoietic tissues, with or without peripheral blood involvement." (PMID 20532179, 2010). "CD5 is highly expressed in T-ALL and T-cell lymphoma in addition to a fraction of B cell malignancies, such as mantle cell lymphoma (MCL) and chronic lymphocytic leukemia (CLL), rather than hematopoietic stem cells and natural killer (NK) cells." (PMID 39462383, 2024). "Immuno-phenotypic and Immuno-histochemistry analyses were positive for Cyclin D1, CD5, CD20 and BCL2, but negative for CD10, CD23 and BCL6, which confirms which confirmed the diagnosis of stage IV mantle cell lymphoma with intact bowel resection margins." (PMID 38954973, 2024). "Aside from mantle cell lymphoma (MCL), discussed in detail in the following section, prolymphocytic leukemia (PLL), lymphoplasmacytic lymphoma (LPL), splenic marginal zone lymphoma (SMZL) and hairy cell leukemia (HCL) may be positive for CD5." (PMID 34898558, 2021). "Based on CD20 and CD5 coexpression without CD23 expression, a differential diagnosis of atypical CLL, CD5 positive marginal zone lymphoma, or cyclin D1 negative mantle cell lymphoma was considered." (PMID 24868472, 2014). "Immuno histochemistry and immunophenotypic analyses were positive for Cyclin D1, CD20, CD5 and CD 79a, but negative for BCL6, CD23 and CD10, thus confirming the diagnosis of mantle cell lymphoma." (PMID 19646237, 2009).
mantle cell lymphoma (continued). "The histo morphology and the immunophenotypic analysis were consistent with a mantle cell lymphoma – positive for Cyclin D1, CD20, CD79a and CD5; negative for BCL16, CD23 and CD10." (PMID 19646237, 2009). "Negative CD5, CD23, and cyclinD1 also help differentiate between small lymphocytic lymphoma/chronic lymphocytic leukemia (SLL/CLL) and mantle cell lymphoma, while CD10 helps distinguish follicular lymphoma; therefore, patients are likely to be considered to have pulmonary MALT-MZL." (PMID 37713822, 2023). "The specimens revealed mantle cell lymphoma, with immunohistochemistry stains positive for CD20, Bcl-2, cyclin D1, SRY-box transcription factor-11 (SOX-11), immunoglobulin D (IgD) and immunoglobulin M (IgM) but negative for CD3, CD5, CD10 and CD23." (PMID 34442137, 2021). "Furthermore, there can be CD5-negative mantle cell lymphomas and cyclin D1-negative (BCL1-negative) mantle cell lymphomas too." (PMID 23691402, 2013). "CD5+ DLBCL can be differentiated from pleomorphic and blastoid mantle cell lymphoma (MCL) by the absence of cyclin D1 and SOX11." (PMID 39684922, 2024). "CD5, CD10, and cyclin D1 are classically negative, aiding in differentiation of MALT from other low-grade B-cell lymphomas such as chronic lymphocytic lymphoma (typically CD5 positive), mantle cell lymphoma (typically CD5 positive), and follicular lymphoma (typically CD10 positive)." (PMID 26178711, 2015).